SPARC (secreted protein acidic and cysteine rich)
Diseases named in the same sentence as SPARC in open-access papers (continued):
Sharing a sentence is not in itself a finding about the gene and the disease.
tumor (continued). "However, this link was widely reported both at transcript and protein levels, both in cell lines and primary tumor tissues and was also in vitro confirmed in our study, since SPARC expression was restored in the UIP lung cell line FF24 upon treatment with the demethylating agent 5-Aza-Cdr." (PMID 40970095, 2025). "Therefore, GP60 and SPARC can be key targets for tumor therapy." (PMID 38323081, 2024). "However, tumor growth was reduced when SPARC was knocked down in MGC803 cells." (PMID 39424639, 2024). "Furthermore, albumin enhances transport of paclitaxel across endothelial cells mediated by a 60 kDa glycoprotein (gp60) receptor on the endothelial cell surface and accumulates in the tumour area by binding to the extracellular protein Secreted Protein Acidic Rich in Cysteine (SPARC)." (PMID 39598496, 2024). "In addition, SPARC can alter the tumor microenvironment by dampening immune cell infiltration." (PMID 38650694, 2024). "In addition to GP60-mediated tumor distribution, there are reports that the secreted protein acidic and rich in cysteine (SPARC) may be attributed to the tumor distribution and uptake of albumin." (PMID 37049985, 2023). "Moreover, SPARC has been shown by several studies to be a key protein that attracts many kinds of cancer cells to the bone microenvironment and can be used as a prognostic indicator of tumor severity and/or aggressiveness." (PMID 36918772, 2023). "Notably, despite the controversial functions on angiogenesis, SPARC may directly or indirectly contribute to tumor angiogenesis in MESO." (PMID 37509139, 2023). "Further, the protein SPARC (secreted protein acidic and rich in cysteine) regulates interactions between cells and their surrounding extracellular matrix, and has shown seemingly contradictory effects on tumor progression in both preclinical and clinical studies." (PMID 37803074, 2023). "However, the biological function of ovarian SPARC in the non-tumor context remains undetermined." (PMID 37158892, 2023). "Moreover, it is noteworthy that FAP and SPARC gene expression analysis in primary BCAFs and paraffin-embedded BC tissues showed that our in vitro tumor stromal microenvironment could be comparable to in vivo tumor stromal microenvironment." (PMID 35743318, 2022). "Furthermore, SPARC proteins (Secreted Protein, Acidic, and Rich in Cysteine) that bind to the albumin-bound drugs in the tumor extracellular matrix contribute to a homogeneous tumor tissue distribution." (PMID 35888170, 2022). "Thus, SPARC has been investigated as a potential therapeutic target, where the presence of SPARC in the tumour stroma could be used to deliver albumin-conjugated molecules into the tumour and TME." (PMID 34336679, 2021). "Also in other malignancies SPARC was reported to affect anti-tumor immune responses." (PMID 33466303, 2021). "However, whether this indicates that MPM tumor tissue is transforming into a sarcomatoid or mesenchymal direction due to high stromal SPARC expression or if high stromal SPARC is already present in more sarcomatoid‐like MPM tumors remains speculative." (PMID 33955203, 2021). "However, the impact of the SPARC expression on the association between tumor cells and the adjacent stromal cells has not been well determined." (PMID 33579227, 2021). "Thus, SPARC has been found to play an important role in tumor progression." (PMID 34912848, 2021). "Interestingly, stromal SPARC expression correlated negatively with the MPM tumor cell marker staining (combination of CK5, calretinin, and CK5/6) (Spearman's rho: −0.432; p = 0.001) and positively with tumor cell PDGFRB expression (Spearman's rho: 0.314; p = 0.008)." (PMID 33955203, 2021). "Expression intensities of SPARC, COL1A1, COL5A1, COMP, IBSP, and THBS4 were interpreted in tumor stroma, as they were associated with ECM-related pathways, and the expression intensity of SORD was interpreted in tumor cells, as it was associated with the EMT pathway." (PMID 34503278, 2021).
tumor (continued). "Instead, tumor-specific and context-dependent activation of subset of genes with distinct functions (e.g., SPARC, FN1, MMP7, ZEB1, ECM1) synergistically promoting, for example, collective cell migration upon interaction with the stromal microenvironment, may represent a more likely scenario." (PMID 34036938, 2021). "Likewise, SPARC was reported to have context and tumor dependent impacts on tumor progression." (PMID 33987095, 2021). "Although the EPR effect and the interaction of albumin with gp60 receptor and SPARC can enhance the accumulation of drug-loaded albumin nanoparticles in tumors, they still have some drawbacks, such as insufficient tumor targeting and weak tumor tissue penetration." (PMID 34869202, 2021). "Therefore, molecules such as Cav-1 or SPARC could be tumour-penetrative biomarkers, as well as prognostic biomarkers, for nab-PTX." (PMID 32532230, 2020). "Collagens, proteoglycans, glycoproteins, metalloproteinases, and matricellular proteins, such as SPARC and osteopontin, are synthesized by mesenchymal elements and partially by Mo, generating heterogeneous mixtures undergoing continuous remodeling under the pressure of tumor growth and inflammation." (PMID 32296632, 2020). "In particular, it has been shown that low expression levels of matricellular SPARC can modulate cell migration in different types of cancer cells, and these observations led researchers to hypothesize a specific role of SPARC in the inhibition of tumour progression and invasiveness." (PMID 31652569, 2019). "Here, the tumor growth inhibitory properties of the system were verified both in the subcutaneous and intracranial models of the disease, significantly highlighting the importance of Gp60 and SPARC in ANV transport, also when produced via the desolvation method." (PMID 31195727, 2019). "However, the functions of SPARC are highly heterogeneous among tumour types." (PMID 31139014, 2019). "Therefore, we can speculate that SPARC expression could influence stroma responsiveness during tumor formation, representing an indicator of the disease at its earlier phases." (PMID 30227835, 2018). "Thus, the prognostic value of tumor SPARC expression remains uncertain." (PMID 29623263, 2018). "Interestingly, however, the overexpression of SPARC was observed in certain types of tumors; thus, it may act as an indicator of tumor progression." (PMID 29065446, 2017). "This evidence might suggest stromal SPARC is also a factor to induce tumor progression." (PMID 28718842, 2017). "Using gene expression analysis and functional tests on purified TAM we revealed that increased tumor growth in wt mice was accompanied by enhanced endocytic clearance function of TAM which was characterized by enforced intracellular uptake of tumor growth inhibiting factor SPARC." (PMID 27105498, 2016). "However, strong trend for decreased SPARC expression in large tumors (stage T3) compared to stages T1 and T2 was observed and reached marginal significance (p=0.0696, Kruskal-Wallis test) suggesting inhibitory role of SPARC in tumor growth." (PMID 27105498, 2016). "However, tumor formation in immune compromised mice demonstrated that the focal expression of SPARC can be regained following inoculation of TICs from both SPARC transfected and non- SPARC transfected As+3-and Cd+2-transformed cell lines." (PMID 26783756, 2016). "However, immunohistochemistry visualizes each individual cell and this technique complimented that of western blotting by demonstrating a low level of focal expression (less than 10%) in the tumor transplant generated from one SPARC-transfected cell line (As#3)." (PMID 26783756, 2016). "In this respect, SPARC represents an interesting molecule as it exerts distinct roles on cancer cells and tissue-specific stromal cells and modulates the interactions of cancer cells with the cellular and acellular components of the surrounding tumor microenvironment (TME)." (PMID 27564266, 2016).
tumor (continued). "Importantly, since SPARC binds albumin with a high affinity, high SPARC tumor levels could enhance the accumulation of albumin within the tumor tissue, and improve the response to nanoparticle albumin-bound (nab)-paclitaxel in a targeted way." (PMID 27421134, 2016). "Presumably, SPARC could act as a tumor suppressor, tumor promoter or pro-invasive factor." (PMID 27803395, 2016). "SPARC has been hypothesized to support tumour uptake of Abraxane®." (PMID 26925240, 2016). "The rapidly proliferating cells in the absence of SPARC along with activation of pro-oncogenes and loss of tumor suppressors generate increased levels of ROS, a manifestation of altered cellular metabolism, may induce aerobic glycolysis or Warburg effect." (PMID 27564266, 2016). "Also, the peptides of SPARC that are present and interacting with the tumor microenvironment could account for the varying effects between cancer types." (PMID 27544129, 2016). "Western blotting of lysates compared for the tumor transplants generated from the SPARC-transfected As+3-and Cd+2-transformed cell lines demonstrated no expression of the SPARC protein for the tumors generated from the As#3, As#6, and Cd#1 cell lines transfected with SPARC." (PMID 26783756, 2016). "In cancer, SPARC may either promote or inhibit tumor growth depending upon the tumor type." (PMID 27776337, 2016). "Thus, SPARC may have additional therapeutic benefit by enhancing the delivery of other molecules transported by albumin to tumor tissues." (PMID 27776337, 2016). "Thus, in primary carcinoma SPARC distributed principally in tumour cells, compared to the stroma." (PMID 26703564, 2015). "Furthermore,studies have showed that SPARC is an albumin-bound protein that is rich in tumormatrix and may plays an important role in absorbing Abraxane into the tumor site." (PMID 25239521, 2014). "However, additional experiments may be required to completely rule out the involvement of PAI-1 in the cooperative interaction between our tumor cell subpopulations, albeit secondary to modulation of SPARC levels." (PMID 25331979, 2014). "However, further investigations are necessary to determine whether NAB-paclitaxel exploits SPARC expression to target tumor cells." (PMID 24484617, 2014). "Moreover, SPARC was abundantly localized within the stroma adjacent to the tumor." (PMID 24396828, 2013). "Consequently, tumor-bearing SPARC−/− mice experienced increased morbidity and decreased survival." (PMID 22348081, 2012). "We suspected that the diminished ECM associated with the absence of host SPARC might enhance tumor progression by altering growth factor localization and availability." (PMID 22348081, 2012). "Indeed, our studies show that inhibition of SPARC leads to increased tumor cell survival." (PMID 22480225, 2012). "SPARC expression may depend on histological type of the tumour, or vice versa." (PMID 22957090, 2012). "Consequently, SPARC expression may alter the angiogenic balance in tumours by down-regulating a series of neovascularisation promoting factors." (PMID 22957090, 2012). "Therefore, using SPARC as a therapeutic target could result in the desired decrease of tumor invasion, but might also result in an undesired increase in tumor proliferation." (PMID 22480225, 2012). "Importantly, these data indicate that SPARC-expressing tumor cells survive better in TMZ (44-fold)." (PMID 22480225, 2012). "These migratory processes require the differential regulation of adhesive and anti-adhesive molecules, and it has been suggested that SPARC may play a key role in the initial processes of tumour invasiveness and ECM modulation is due to its anti-adhesive properties." (PMID 21818290, 2011). "This suggests that the levels of FOXP3 expression, as for SPARC, in the patient's primary tumour may play an important prognostic role that could assist in distinguishing between stage II cancers that would, and would not, benefit from post-operative adjuvant chemotherapy." (PMID 21818290, 2011).
tumor (continued). "Our current study demonstrates that the pro-apoptotic activity of SPARC is confined to a specific region of the protein, and that a recombinant peptide containing this smaller region alone is capable of conferring greater apoptosis and tumor regression in vivo." (PMID 22069448, 2011). "Our findings indicate that while SPARC's N-terminus domain inhibits tumor growth, the follistatin-like (FS-) domain alone may have growth-promoting properties, as xenografts overexpressing recombinant proteins of this fragment had significantly shorter doubling times than control xenografts." (PMID 22069448, 2011). "Therefore, differences in tumor-specific protease expression may account for the differences in SPARC's biological behavior in tumorigenesis and different cancers." (PMID 22069448, 2011). "Among the many biological processes modulated by SPARC, its anti-adhesive, pro-migratory, and anti-apoptotic properties on certain cell types in addition to its capacity to regulate matrix metalloproteinase (MMP) expression and activity have been associated with increased tumor agresiveness." (PMID 19337591, 2009). "Given the differential degree of methylation of the SPARC promoter between the tumour and normal colon within the same individual, this suggests that the degree of hypermethylation in the SPARC promoter within the tumour is likely related to the diseased state." (PMID 18458674, 2008). "The overexpression of SPARC in a variety of malignancies excludes it as a suitable diagnostic biomarker for any specific tumour, although it displays promise as a prognostic marker of tumour progression and advanced cancer stage." (PMID 15558074, 2004). "In addition to being passively accumulated, albumin displays natural tumor affinity via interactions with specific receptors, such as glycoprotein 60 (gp60), on vascular endothelial cells and secreted protein acidic and rich in cysteine (SPARC), which is often overexpressed in tumor cells." (PMID 41489768, 2026). "SPARC, a modulator of the extracellular matrix, can influence the tumor microenvironment and EMT, facilitating tumor growth and invasion." (PMID 40559998, 2025). "Promising approaches such as targeting SPARC-mediated nanoparticle uptake, HSF1 and TGF-βRII signaling, or CAF-derived exosomal miRNAs, offer innovative avenues to disrupt tumor–stroma crosstalk." (PMID 41583435, 2025). "In parallel, ECM remodeling was evident, with increased expression of SPARC and FN1 and collagen fiber alignment, reflecting an invasive tumor phenotype." (PMID 41008923, 2025). "We subsequently performed IHC experiments on mouse tumour tissues and found that the intensity of SPARC, P‐STAT3, and HK2 staining was significantly greater in tumour tissues from the OE‐SPARC group than in those from the control group." (PMID 40415238, 2025). "These NPs are modified with T12 peptide, allowing them to selectively target tumor cells and TAM via Secreted Protein Acidic and Rich in Cysteine (SPARC) and TfR receptors, enabling dual targeting." (PMID 40733107, 2025). "Using murine models, we elucidated the mechanism linking ECM3 to PD-1− Tregs: SPARC, a gene within the ECM3 signature, induces IL-23 in the tumor microenvironment." (PMID 40890836, 2025). "SPARC, part of the ECM glycoprotein family, is significantly expressed in GC and correlates with depth of tumor invasion, lymph node metastasis, TNM staging, and poor OS." (PMID 41262238, 2025). "The prominence of POSTN, SPARC, and TGFBI among the shared hubs also underscores the role of TGF-β pathway activity and a myofibroblastic stroma in both tumor types." (PMID 40872572, 2025). "The identification of gene co-expression modules containing classical EMT markers (e.g., VIM, ZEB1, SNAI2) alongside ECM-related genes (COL1A1, FN1, SPARC, LOX) underscores a tightly coordinated interaction driving tumor cell plasticity and invasion." (PMID 40943497, 2025).
tumor (continued). "ITGA5 also functions as the transmembrane receptor, facilitating SPARC-induced ECM changes mediated through fibronectin, which activates fibroblasts to induce dominant ECM alterations that promote tumour cell proliferation and migration in the stroma." (PMID 39865173, 2025). "Previous studies have showed that macrophage-derived SPARC (secreted protein acidic and rich in cysteine) regulates ECM deposition and cell-ECM interactions and enhances tumor cell invasion and adhesion to other ECM components." (PMID 38293522, 2024). "The experimental results showed that albumin nanoparticles modified by the technology of reverse QTY code can maintain its biological activities and target tumor tissue or cells efficiently via the GP60 receptor and SPARC pathway." (PMID 38323081, 2024). "The results revealed significant differences between the tumor and paratumor tissues regarding the expression of FAP, secreted protein acidic and cysteine rich (SPARC), and tenascin C (TNC), which are closely related to HSCs’ function." (PMID 38740736, 2024). "The main reason for this effect was that albumin nanoparticles utilized the GP60- and SPARC-mediated pathway for targeted DOX delivery, and the effect resulted in significant inhibition of tumor growth and lower exposure of major organs to DOX." (PMID 38323081, 2024). "Tumor histology demonstrated altered ECM structure and decreased macrophage infiltration, suggesting that SPARC mediates interactions of tumor cells with the ECM." (PMID 38928185, 2024). "We confirmed the localization of the SPARC protein and the ICG fluorescence signal in the resected tumor." (PMID 36614294, 2023). "Compared with malignant cells, YAP activation in PSCs triggers the secretion of SPARC, an ECM protein, to suppress tumor growth." (PMID 36906534, 2023). "Of note, seventeen of thirty-nine proteins are reported as urine biomarkers in different diseases, of which eight proteins (PEBP1, EPS8L2, SERPINA1, FGA, SPINT1, CD55, SPARC, and GINM1) are related to neoplastic disease in urine specimens." (PMID 36918772, 2023). "In addition, boron uptake when conjugated to albumin could be attributed not only to the EPR effect, but also to an increase in catabolism by the tumor or through other albumin-specific transporters such as gp60 and secreted protein acidic and rich in cysteine (SPARC)." (PMID 37759639, 2023). "The modification of lactoferrin and the adsorption of endogenous albumin have a dual-targeting effect on the receptors of both LRP1 and Secreted protein acidic and rich in cysteine (SPARC), which are overexpressed in tumor cells and immune cells." (PMID 37242604, 2023). "Four of the top five most up-regulated glycoproteins in tumour ECM – thrombospondin-1 and -2, SPARC and peroxidasin – formed a connected subnetwork, pointing to their common functional roles in organising the collagen ECM and regulating cell–ECM adhesion." (PMID 37397358, 2023). "In summary, RORA and SPARC are crucial downstream targets of TET2 that connect TET2 and its tumour suppression effects." (PMID 37620362, 2023). "Mesenchymal stem cells induce tumor stroma formation and epithelial-mesenchymal transition (EMT) through SPARC expression in colorectal cancer." (PMID 37509139, 2023). "Peritumoral stromal cells (tumor-associated fibroblasts and macrophages) were the principal source of SPARC in the TME, and exogenous SPARC increased tumor cell invasion." (PMID 37577749, 2023). "The enrichment of T-cells and fibroblasts/endothelial cells in tumor tissues was verified through immunofluorescent staining of CD3D and SPARC, respectively." (PMID 35974387, 2022). "SPARCL1, also known as Hevin, works together with SPARC to diminish angiogenesis HCC and delay in vivo tumor growth." (PMID 35111225, 2022). "ECM secretion by cancer cells in low-adhesion environments has been suggested previously; for example, increased expression of SPARC, MPG and SPON2 has been reported in circulating tumour cells from patients." (PMID 36546396, 2022).